ENSG00000274693
Gene: Miscellaneous RNA gene on chromosome 4 (3,069,977 to 3,070,151, forward strand). Ensembl gene ENSG00000274693.
Gene Ontology:
Biological process: regulation of gene expression